PML (PML nuclear body scaffold)
Diseases named in the same sentence as PML in open-access papers (continued):
Sharing a sentence is not in itself a finding about the gene and the disease.
acute promyelocytic leukemia (continued). "An in vitro study demonstrated that arsenite destabilizes lysosomes, releasing proteases which act on the promyelocytic leukemia and retinoic acid receptor α (PML/RARα), a fusion protein expressed by APL cells." (PMID 34243768, 2021). "Promyelocytic leukemia nuclear bodies (PML-NBs) are multiprotein complexes with PML as the main building component." (PMID 33849647, 2021). "The PML protein is a member of the TRIM family of ubiquitin/SUMO ligases discovered through its implication in acute promyelocytic leukemia (APL)." (PMID 33075130, 2021). "Pin1 also stabilizes the oncogenic fusion protein PML-RARα, which disrupts the localization of wild-type PML from nuclear bodies to numerous micro speckles and induces a maturation arrest in promyelocytic leukemia." (PMID 33807199, 2021). "In another report, the dysregulation of basal DDIT4 gene expression in several cancer types (e.g. lung, breast, prostate) can be altered by promyelocytic leukemia (PML) and lead to mTOR activation and cancer progression." (PMID 32497068, 2020). "Promyelocytic leukemia nuclear bodies (PML NBs) are multimolecular structures formed predominantly by the PML protein." (PMID 32157726, 2020). "This review focuses on cancers expressing well-known annexins, with a special emphasis on ANXA8, which is an annexin that was found to be overexpressed for the first time in acute promyelocytic leukemia (APL) carrying a fusion gene involving both PML and RARA." (PMID 32823855, 2020). "In contrast, a fusion protein of PML with retinoic acid receptor α (PML-RARα), resulting from frequent translocation in acute promyelocytic leukemia (t15;17), suppresses CHK2 and inhibits its autophosphorylation." (PMID 33322746, 2020). "The ‘speckled’ nuclear distribution of Sp100 predominantly colocalizes with promyelocytic leukemia-nuclear bodies (PML-NBs)." (PMID 33598438, 2020). "Acute promyelocytic leukemia subtype M3 (AML M3) is a subtype of AML characterized by the presence of promyelocytic leukemia-retinoic acid receptor alpha (PML-RARA) genes fusion." (PMID 32243411, 2020). "Sp100 isoforms are resident component proteins of promyelocytic leukemia-nuclear bodies (PML-NBs), dynamic nuclear sub-structures which regulate host immune defenses against many pathogens." (PMID 33598438, 2020). "The importance of PML protein was first reported in acute promyelocytic leukemia, a rare but extremely malignant condition due to the abnormal fusion of PML protein with the retinoic acid receptor α." (PMID 32154186, 2020). "By targeting PML or PML-RARa for ubiquitination mediated degradation arsenic compounds successfully applied in the treatment of acute promyelocytic leukemia (APL)." (PMID 33353561, 2020). "The first cancer showing ANXA8 upregulation was reported in acute promyelocytic leukemia (APL), which induces the differentiation arrest of promyelocytes due to defective RA signaling caused by RARA fusion genes as the PML-RARA gene." (PMID 32823855, 2020). "A microfluidic assay for the detection of promyelocytic leukemia (PML)-retinoic acid receptor α (RARα) fusion protein was developed." (PMID 33255664, 2020). "The fusion protein PML-RARα occurs in 95% of acute promyelocytic leukemia cases and is considered as diagnostically relevant." (PMID 33255664, 2020). "The PML/RARα fusion protein acts in concert with cooperative genetic events in the development of acute promyelocytic leukemia (APL)." (PMID 33298855, 2020). "Promyelocytic leukemia (PML) bodies are dynamic intracellular structures that recruit and release a variety of different proteins in response to stress, virus infection, DNA damage and cell cycle progression." (PMID 31416160, 2019).
acute promyelocytic leukemia (continued). "Promyelocytic leukemia‐NBs act as storage or catalytic platforms for numerous proteins providing a microenvironment for potential mutual regulation between PML and its interacting components." (PMID 30927552, 2019). "Stunningly, simple chemicals – retinoic acid and arsenic – because of their ability to regulate PML stability, have emerged as powerful tools to treat and reverse PML-related diseases, like acute promyelocytic leukemia." (PMID 31405317, 2019). "Here we review the biochemical and biophysical transitions that occur in PML bodies during mitosis and discuss this in light of post-mitotic nuclear import, cell fate decision and acute promyelocytic leukemia therapy." (PMID 31416160, 2019). "Guarnerio studied two types of leukemia, acute promyelocytic leukemia (APL) with translocation between PML and RARα, and AML with translocation between MLL and AF9." (PMID 31306100, 2019). "TRIB3 promotes PML-RARα-driven acute promyelocytic leukemia by interacting with PML-RARα and regulating PML-RARα degradation." (PMID 31844113, 2019). "In acute promyelocytic leukemia, its main component, the PML protein, is fused with the retinoic acid receptor α, which causes disorganization of PML-NB." (PMID 31285264, 2019). "Exposure to IRC117539 promotes AR sumoylation and ubiquitination, reminiscent of therapy-induced PML/RARA degradation in acute promyelocytic leukemia." (PMID 31431473, 2019). "This catabolic pathway is strikingly similar to the recently uncovered mechanism of therapy-induced PML/RARA degradation in acute promyelocytic leukemia and therapy-induced Tax oncoprotein degradation in adult T-cell lymphoma." (PMID 31431473, 2019). "A hallmark of acute promyelocytic leukemia (APL) is the expression of PML/RARα fusion protein." (PMID 31592194, 2019). "Acute promyelocytic leukemia (APL) is mostly caused by the PML-RARA fusion protein." (PMID 30830246, 2019). "In acute promyelocytic leukemia or adult T-cell lymphoma, arsenic-induced, SUMO-triggered ubiquitination and proteasomal destruction of driver oncoproteins (PML/RARA and Tax, respectively) were shown to be the underlying mechanism for therapy response." (PMID 31431473, 2019). "In acute promyelocytic leukemia (APL), genetic or chemical inhibition of Pin1 can induce the degradation of the disease-causing fusion oncogene PML-RARα, which causes APL through blockage of promyelocyte differentiation and promotion of self-renewal capacity." (PMID 29848341, 2018). "Promyelocytic Leukemia (PML) bodies are detected by immunostaining of their PML protein and are usually spherical in shape and vary in diameter from 0.2–1 μm and in number from about 5–30 per nucleus." (PMID 28910577, 2018). "Promyelocytic leukemia (PML) nuclear bodies (NBs) control viral infections by preventing the onset of lytic infection." (PMID 30235352, 2018). "Research has shown that binding of RXRα to PML–RARα is essential in the development of acute promyelocytic leukemia in transgenic mice, further illustrating the carcinogenicity of RXRα when it functions inappropriately." (PMID 30093910, 2018). "Promyelocytic leukemia acts as a first line of host defense in response to viral infections; however, viruses have evolved ways to counteract PML-mediated antiviral activities." (PMID 29922292, 2018). "Promyelocytic leukaemia-retinoic acid receptor α (PML-RARα) is a fusion protein that plays an important role in acute promyelocytic leukaemia (APL)." (PMID 28535767, 2017). "PML (promyelocytic leukemia)/TRIM19 belongs to the tripartite motif (TRIM) protein superfamily, the members of which share a conserved tripartite architecture: a RING domain, one or two B-boxes, and a coiled-coil domain." (PMID 28656178, 2017). "In acute promyelocytic leukemia, PML NBs are perturbed because oncogenic PML-RARα (chimera involving PML and the retinoic acid receptor α) disrupts these structures into multiple dispersed smaller bodies." (PMID 29206178, 2017).
acute promyelocytic leukemia (continued). "All-trans retinoic acid (ATRA) and/or arsenic trioxide (ATO) administration leads to granulocytic maturation and/or apoptosis of acute promyelocytic leukemia (APL) cells mainly by targeting promyelocytic leukemia/retinoic acid receptor alpha (PML/RARα)." (PMID 28492552, 2017). "In acute cases of promyelocytic leukemia, the fused oncogenic protein PML-RARα (promyelocytic leukemia-retinoic acid receptor-α) represses hematopoietic cell differentiation genes via recruiting an HDAC." (PMID 28783137, 2017). "Induction of ROS through niclosamide treatment in AML, parthenolide treatment in AML and CML, and arsenic trioxide treatment in PML (promyelocytic leukemia) target CSCs." (PMID 28160777, 2017). "Among several distinctive chromosomal translocations in leukemia, PML/RARα is the most frequent translocation in acute promyelocytic leukemia (APL), which can generate one or more f-circRNAs from this fusion gene." (PMID 29349062, 2017). "Promyelocytic leukemia nuclear bodies (PML-NBs) are PML-based nuclear structures that regulate various cellular processes." (PMID 27211601, 2016). "CHEK2 phosphorylates PML (Promyelocytic Leukemia) and appears to require PML for subsequent autophosphorylation." (PMID 26732650, 2016). "Similar to our method, they used a self-annealing primer and successfully identified PML-RARA transcripts in acute promyelocytic leukemia." (PMID 26999437, 2016). "The PML (promyelocytic leukemia) gene was originally identified based on its localization at the break point of the t(15:17) chromosome translocation found in most cases of acute promyelocytic leukemia." (PMID 27042198, 2016). "All-trans-retinoic acid (atRA), a biologically active form of Vitamin A and a cytodifferentiating agent is being successfully used for the treatment of acute promyelocytic leukemia (APL) in which RARα is fused to PML." (PMID 27286261, 2016). "ND10s, also known as PML (promyelocytic leukemia) nuclear bodies or PML oncogenic domains, are nuclear structures that are composed of over 150 constituents." (PMID 27048561, 2016). "The PML gene was identified at the break point of the t(15:17) chromosome translocation of acute promyelocytic leukemia, which results in the generation of oncogenic PML–RARα fusion protein." (PMID 27200299, 2016). "BNRF1 wt co-localized strongly with DAXX at punctate subnuclear structures previously shown to be PML-NBs (promyelocytic leukemia-nuclear bodies)." (PMID 27581705, 2016). "When cells enter senescence, HIRA and the other members of the HUCA complex, CABIN1 and UBN1, localizes in PML (ProMyelocytic Leukemia) nuclear bodies (PML-NBs) and this process is required for SAHF formation." (PMID 27602048, 2016). "Nuclear speckles, Cajal bodies, and promyelocytic leukaemia nuclear bodies (PML-NBs) were evaluated by immunofluorescence microscopy and Western blot." (PMID 26389938, 2015). "PML is the core component of subnuclear structures called PML nuclear bodies (PML-NBs), which are disrupted in acute promyelocytic leukemia cells." (PMID 26539288, 2015). "For the least characterized PYHIN protein, IFIX, we observed enriched association with an interaction cluster formed by components of promyelocytic leukemia (PML) nuclear bodies." (PMID 25665578, 2015). "RNF4 localizes to PML (promyelocytic leukaemia)-NBs (nuclear bodies), and we and others have identified the PML protein and the oncogenic PML-RARα (retinoic acid receptor α) fusion protein as its substrates." (PMID 24151981, 2014). "Translocation involving the PML locus (15q22) resulting in the expression of a fusion protein PML-RARα is found in the majority of acute promyelocytic leukemia cases." (PMID 24886876, 2014).
acute promyelocytic leukemia (continued). "Arsenic trioxide (As2O3) induces differentiation and apoptosis of acute promyelocytic leukemia (APL) cells by binding to the PML-RARα oncoprotein, and treatment with As2O3 has been shown to increase remission rates and prolong survival in patients." (PMID 24678763, 2014). "At low concentrations (0.25–1.0 μM in plasma) the drug blocks cell growth and promotes terminal differentiation by disrupting the promyelocytic leukemia-retinoic acid receptor alpha (PML-RARα) oncogenic fusion protein, characteristic of APL." (PMID 25506699, 2014). "Promyelocytic leukemia nuclear bodies (PML NBs) are comprised of PML and a striking variety of its associated proteins." (PMID 24728382, 2014). "The NB4 cell line was established from an acute promyelocytic leukemia patient that expresses the PML-RARα fusion protein." (PMID 25115845, 2014). "RNF4 (RING finger protein 4) is a STUbL [SUMO (small ubiquitin-related modifier)-targeted ubiquitin ligase] controlling PML (promyelocytic leukaemia) nuclear bodies, DNA double strand break repair and other nuclear functions." (PMID 24151981, 2014). "A known RNF substrate is SUMO-PML (promyelocytic leukemia), a molecule involved in the formation of PML-nuclear bodies and implicated in the cellular antiviral response and tumor suppression." (PMID 23990779, 2013). "An attempt was made to use functionalized graphene oxide (GO) to detect the Promyelocytic leukemia/Retinoic acid receptor α fusion gene (PML/RARα fusion gene), a marker gene of acute promyelocytic leukemia." (PMID 23787474, 2013). "Well-established oncogenic roles for NCOR1 and NCOR2/SMRT have been elucidated in acute promyelocytic leukemia that results from a fusion between RARα, and either the promyelocytic leukemia (PML) or promyelocytic leukemia zinc finger (PLZF) genes." (PMID 23098689, 2013). "K-Rta preferentially degrades sumoylated proteins such as PML (promyelocytic leukemia) which negatively regulates viral replication." (PMID 23990779, 2013). "Promyelocytic leukemia nuclear bodies (PML-NBs) are multicomponent subnuclear organelles that are involved in a range of host cell functions in response to stress including genotoxic stress and that have been clearly associated with DNA damage." (PMID 24116215, 2013). "In accordance with the preceding interpretation, a study reported the recruitment of BACH2 upon oxidative stress in promyelocytic leukemia nuclear (PML) nuclear bodies." (PMID 23936317, 2013). "The cells exhibited typical features of cellular senescence with the expression of SA-β-Gal and of CKI, formation of promyelocytic leukemia (PML) nuclear bodies and of SAHF." (PMID 24116215, 2013). "First evidence came from the PML/RARA oncoprotein responsible of acute promyelocytic leukemia (APL)." (PMID 23847762, 2013). "The telomeres of the ALT cells usually associate with PML (promyelocytic leukemia) nuclear bodies, which are in this context referred to as ALT-associated PML bodies (APBs)." (PMID 24970142, 2012). "Cancer cells that use the ALT pathway exhibit distinct phenotypes such as heterogeneous telomeres and specialised Promyelocytic leukaemia (PML) nuclear foci called APBs." (PMID 22925423, 2012). "Promyelocytic leukemia nuclear bodies (PML-NBs) have been suggested as possible sites for viral replication of polyomaviruses (BKV and SV40), herpes simplex virus (HSV), and adenovirus (Ad)." (PMID 22496654, 2012). "The therapeutic efficacy of arsenic trioxide in acute promyelocytic leukemia is dependent on the SUMOylation of PML–RARα oncoprotein." (PMID 22666381, 2012). "The PML gene is often fused with the retinoic acid receptor α (RARA) gene, which is associated with acute promyelocytic leukemia." (PMID 23157318, 2012). "Promyelocytic leukemia-retinoic acid receptor alpha (PML-RARα) expression in acute promyelocytic leukemia (APL) impairs transforming growth factor beta (TGFβ) signaling, leading to cell growth advantage." (PMID 22053203, 2011).
acute promyelocytic leukemia (continued). "Promyelocytic leukemia nuclear bodies (PML-NBs) are important for the assembly and disassembly of protein complexes, including those with RAD51, RPA, and BRCA1 necessary for HRR (for a recent review)." (PMID 21666281, 2011). "The Epstein-Barr virus (EBV) encoded Latent Membrane Protein 1 (LMP1) has been shown to increase the expression of promyelocytic leukemia protein (PML) and the immunofluorescent intensity of promyelocytic leukemia nuclear bodies (PML NBs)." (PMID 21975125, 2011). "Arsenic is known to induce PML SUMOylation and eventual degradation of PML and is used as a treatment for acute promyelocytic leukemia." (PMID 21305000, 2011). "The well-known PML tumor suppressor involved in promyelocytic leukemia through the PML-RARα rearrangement has also been shown to be required for the maintenance of normal HSCs and CML stem cells." (PMID 21946665, 2011). "When FOXL2 was co-transfected with SUMO-1 in COS-7 cells, co-localization was observed by confocal microscopy in structures reminiscent of PML (promyelocytic leukaemia) bodies." (PMID 20209145, 2010). "We did not however find any significant co-localization with the canonical nuclear speckle marker SC35 (also known as SFRS2) or with PML (promyelocytic leukemia) bodies." (PMID 20824083, 2010). "In NB4 cells, a model from promyelocytic leukemia containing the fusion protein PML-RARα and sensitive to retinoids, the highest concentration of BPA used induces around 38% of apoptosis after 48 hrs." (PMID 19538739, 2009). "The DLP 3D printer MiiCraft Prime could be used to produce microfluidic structures for the detection of the fusion protein PML::RARA for the diagnosis of acute promyelocytic leukemia quickly and cost-effectively." (PMID 39859217, 2025). "While the PML gene is involved in chromosomal translocation typically in acute promyelocytic leukemia, loss of PML protein expression rather than PML mutations or deletions has been demonstrated in various cancers." (PMID 40002221, 2025). "A study revealed that deneddylation of PML /retinoic acid receptor α restores phase separation to reconstitute functional PML nuclear bodies and activates retinoic acid receptor α, the eradication of acute promyelocytic leukemia." (PMID 38481812, 2024). "Interestingly, promyelocytic leukaemia‐nuclear bodies (PML‐NBs) were found to mediate the nuclear reconfiguration of hMSCs triggered by the inflammatory cytokines." (PMID 37864298, 2024). "PML is a tumor suppressor gene in acute promyelocytic leukemia (APL)." (PMID 38725075, 2024). "In some cases, the cytoplasmic distribution of PML is attributed to the absence of NLS in PML due to alternative splicing or mutations, as in the case of acute promyelocytic leukemia." (PMID 39395810, 2024). "SP110 was initially identified within PML (promyelocytic leukemia) nuclear bodies, which are multiprotein complexes located within the nucleus and involved in regulating various nuclear functions such as DNA replication, gene transcription, and epigenetic inheritance." (PMID 38891697, 2024). "Inspired by the paradigm of depleting the PML-RARA fusion protein in acute promyelocytic leukemia using all-trans retinoic acid and arsenic trioxide, we conducted a screen to identify FDA-approved drugs capable of depleting MLL-fusion protein expression in leukemia cells." (PMID 39152521, 2024).